RNA5SP172 (RNA, 5S ribosomal pseudogene 172)
Synonyms: formerly RN5S172
Gene: Ribosomal RNA gene on chromosome 4 (177,457,111 to 177,457,228, reverse strand). Ensembl gene ENSG00000201931.
Homologues: Orthologues: chimpanzee 5S_rRNA (100% identical), guinea pig 5S_rRNA (73% identical), guinea pig 5S_rRNA (65% identical), mouse Gm56012 (63% identical). Paralogues in human: RNA5S1 (79% identical), RNA5S10 (79% identical), RNA5S11 (79% identical), RNA5S12 (79% identical), RNA5S13 (79% identical), RNA5S14 (79% identical), RNA5S15 (79% identical), RNA5S16 (79% identical), RNA5S17 (79% identical), RNA5S2 (79% identical), RNA5S3 (79% identical), RNA5S4 (79% identical), and 26 more.